SIRT3 (sirtuin 3)
Diseases named in the same sentence as SIRT3 in open-access papers (continued):
Sharing a sentence is not in itself a finding about the gene and the disease.
renal failure (3 papers, 2019 to 2022). "Lack of Sirt3 increases CLP-induced renal insufficiency, tubular cell death and apoptosis, mitochondrial dysfunction, and ROS production in a knockout mouse model of AKI46." (PMID 35729330, 2022).
retinal degeneration (3 papers, 2017 to 2022). Degeneration of the retina. "Sirt3 and Sirt5 double-knockout mice (Sirt3KO Sirt5KO) were strikingly more vulnerable to retinal degeneration upon light stress, as assessed by ERG, revealing important roles in photoreceptor survival." (PMID 35165261, 2022). "In this study, we investigated the role of retinal SIRT3 in a mouse model of light-induced retinal degeneration, found that SIRT3 has neuroprotective role in the retina." (PMID 29214052, 2017). "In this study, we investigated the molecular mechanism by which retinal SIRT3-regulated photoreceptor survival in a light-induced retinal degeneration model." (PMID 29214052, 2017). "In this study, we investigated the role of retinal SIRT3 in a light-induced retinal degeneration model using SIRT3 knockout mice." (PMID 29214052, 2017). "We hypothesized that genetic background of SIRT3 KO mice was responsible for the subtle phenotype of light-induced retinal degeneration." (PMID 29214052, 2017). "Moreover, we have previously reported that although mice lacking both SIRT3 and SIRT5 do not exhibit retinal degeneration at baseline, they are more vulnerable to light-induced degeneration." (PMID 30846716, 2019).
schizophrenia (3 papers, 2023 to 2025). A major psychotic disorder characterized by abnormalities in the perception or expression of reality. "In patients with schizophrenia, mitochondrial dysfunction leads to alterations in the activity of mitochondrial Sirt3 protein, exacerbating the accumulation of ROS and intensifying the clinical manifestations of schizophrenia." (PMID 40309794, 2025). "In this study, Sirt3 was diminished in both the PBMCs and ADEs of patients with schizophrenia and negatively correlated with positive symptoms." (PMID 40309794, 2025). "The confounding variables, such as sex, age, and educational background, were adjusted, and the TRPV1 receptor and Sirt3 protein expressions in the PBMCs of the patients with schizophrenia were significantly diminished compared with those of the HC group." (PMID 40309794, 2025). "Prior research conducted in our laboratory indicated that Sirt3 may play a role in reducing the schizophrenia-like behavioral phenotype at adulthood in a 24 h maternal separation Wistar rat model on postnatal day nine." (PMID 40309794, 2025). "A striking aspect of this study was our observation of the regulation of the mitochondrial molecules NAD+/SIRT3 in an animal model of schizophrenia-related behavioral and neuronal impairment together with a mechanistic dissection of the neurobiological intermediaries in both cells and animals." (PMID 37210391, 2023). "An analysis of TRPV1, Sirt3, SOD2, and acetyl-SOD2 in the PBMCs and ADEs of the patients with schizophrenia showed that TRPV1 in the PBMCs exhibited a positive correlation with that in the ADEs." (PMID 40309794, 2025). "In this study, we found a marked downregulation of Sirt3 and upregulation of SOD2 and acetyl-SOD2 in both the PBMCs and ADEs of patients with schizophrenia relative to the controls." (PMID 40309794, 2025). "In this study, the detection of ADEs revealed that, similar to the findings in PBMCs, the TRPV1 and Sirt3 expressions were significantly downregulated, while the SOD2 and acetyl-SOD2 expressions were significantly increased in patients with schizophrenia compared with those of the HC group." (PMID 40309794, 2025). "However, SIRT3’s involvement in the neuronal impairment induced by ELS and whether it is key to the neuroprotective effects of NAM in this model of schizophrenia are uncertain." (PMID 37210391, 2023).
Shock (3 papers, 2015 to 2022). The state in which profound and widespread reduction of effective tissue perfusion leads first to reversible, and then if prolonged, to irreversible cellular injury. "Our results show that treatment with MRS restored the expression of SIRT3, which was decreased by hemorrhagic shock and resuscitation; this restoration of SIRT3 levels likely occurred via upregulated expression of PGC-1α." (PMID 31885797, 2019). "In addition, Sirt3 protects tissues and cells from hemorrhagic shock by inhibiting cellular oxidative stress, necrosis, and apoptosis and alleviating mitochondrial damage and dysfunction." (PMID 31885797, 2019).
systemic sclerosis (3 papers, 2016 to 2023). A chronic disorder, possibly autoimmune, marked by excessive production of collagen which results in hardening and thickening of body tissues. "Both SIRT1 and SIRT3 serum levels were significantly reduced in patients with systemic sclerosis compared to those in controls." (PMID 37483618, 2023). "SIRT3 expression was significantly reduced in systemic sclerosis skin biopsies and transplanted fibroblasts and was inhibited by TGF-ß treatment in normal fibroblasts." (PMID 37483618, 2023). "In systemic sclerosis, a decrease in circulating SIRT1 and SIRT3 levels enhances the severity of cutaneous fibrosis and interstitial lung disease." (PMID 37483618, 2023). "In the last few decades, a growing number of studies have explored the contribution of SIRTs to the pathogenesis of systemic sclerosis, highlighting the significant anti-fibrotic effects of SIRT1 and SIRT3." (PMID 37483618, 2023). "The enhancement of cellular SIRT3 by hexafluorine treatment blocked intracellular TGF-β signalling and fibrotic responses and attenuated the activation phenotype of systemic sclerosis fibroblasts, while the accumulation of mitochondrial and cytoplasmic ROS in fibroblasts was reduced." (PMID 37483618, 2023).
tongue cancer (3 papers, 2020 to 2023). A malignant neoplasm affecting the tongue. "Sirt3 over-expression was observed in a brain tumor family and in a cohort of tongue cancer patients." (PMID 36739437, 2023). "In summary, this study revealed that SIRT3 acts as an oncogene in tongue cancer via regulation of the JNK-Fis1 axis." (PMID 35571098, 2022). "Another report showed that the JNK-FIS1 biological axis is important for mitochondrial stress mediated by Sirtuin 3 (SIRT3) inhibition in tongue cancer." (PMID 33233365, 2020). "The authors used two types of tongue cancer cells (SCC9 and SCC15), in which they demonstrated that SIRT3 silencing led to mitochondrial oxidative stress, energy metabolism disorder, mitochondrial Cyt-C release, and mitochondrial apoptosis activation." (PMID 33233365, 2020).
Venous thrombosis (3 papers, 2017 to 2022). Formation of a blood clot (thrombus) inside a vein, causing the obstruction of blood flow. "The effect of Sirt3 deficiency on platelet and neutrophil activation in vivo was examined by the venous thrombosis model of inferior vena cava stenosis." (PMID 29236713, 2017). "Next we examined the effect of Sirt3 deficiency on platelet and neutrophil activation by physiological agonists in vivo, and whether the deficiency enhances venous thrombosis." (PMID 29236713, 2017). "Recently, the role of oxidative stress in the formation of NET during venous thrombosis was investigated in Sirt3-/- mice subjected to IVC stenosis." (PMID 34449018, 2022). "Obtained data revealed that chronic exposure to IS promotes arterial thrombosis via increased levels of complex tissue factor/factor VII, plasminogen activator inhibitor-1 (PAI-1), platelet activation, as well as decreased aortic levels of SIRT1 and SIRT3." (PMID 30546314, 2018). "In conclusion, the elevation of mitochondrial ROS observed in platelets from Sirt3-/- mice was not strong enough to augment platelet aggregation, and thus, did not impact venous thrombosis." (PMID 29236713, 2017). "We conclude that Sirt3 does not considerably impact NET formation, platelet function, or venous thrombosis in healthy young mice." (PMID 29236713, 2017).
aging (2 papers, 2022 to 2025). A developmental process that is a deterioration and loss of function over time. "The attenuation or ablation of SIRT3 is related to the accelerated development of various aging diseases." (PMID 36012545, 2022). "Moreover, as a member of mitochondrial sirtuins, SIRT3 plays a pivotal role in cell homeostasis and is involved in a variety of aging‐related diseases." (PMID 40104207, 2025).
alcohol fatty liver disease (2 papers, 2018 to 2022). "The SIRT1/SIRT3-FOXO3a pathway is activated by Liraglutide to promote autophagy in non-alcohol fatty liver disease." (PMID 29896416, 2018). "Sirtuin 1 (SIRT1), the SIRT1/NF-κB axis, SIRT3, and SIRT4 play a major role in regulating hepatic lipid metabolism, controlling oxidative stress, and mediating chronic inflammation in NAFLD and alcoholic fatty liver disease." (PMID 35203484, 2022).
alcoholic liver diseases (2 papers, 2019 to 2023). A disorder caused by damage to the liver parenchyma due to alcohol consumption. "Such carbonyl group adduction has also been described in other pathological conditions, for example, in alcoholic liver disease, where the covalent modification of SirT3 by 4-HNE at Cys280 (a critical zinc-binding residue) was identified by tandem mass spectrometry." (PMID 38129330, 2023).
alpha-synucleinopathies (2 papers, 2017 to 2020). "Overall we confirm the potential application of SIRT3 activators as future targets for pharmacological strategies against neurodegeneration in PD and related alpha-synucleinopathies." (PMID 31931835, 2020).
arteriosclerosis (2 papers, 2023 to 2024). A vascular disorder characterized by thickening and hardening of the walls of the arteries. "AR-C17 can protect against arteriosclerosis in endothelial cells and apolipoprotein E-deficient mice by modulating Sirt3 signaling." (PMID 38613012, 2024). "A previous study reported that AR-C17 could protect endothelial cells against arteriosclerosis by regulating the Sirt3 signaling pathway." (PMID 37960251, 2023).
bacteremia (2 papers, 2017 to 2019). "Together with the fact that SIRT3−/− and SIRT5−/− mice are susceptible to bacterial sepsis like wild-type mice, these observations strengthen the development of pharmacological modulators of the activity of mitochondrial sirtuins for clinical purposes." (PMID 31632409, 2019). "However, bacteremia was very low when compared to liver and spleen bacterial burdens, which were not different between SIRT3+/+ and SIRT3−/− mice." (PMID 28634345, 2017).
benign thyroid tumor (2 papers, 2022 to 2023). "However, SIRT3 was reported to be highly expressed in DTC compared to benign thyroid tumor and might involve mitochondrial alterations." (PMID 35136826, 2022).
brain tumor (2 papers, 2015 to 2023). "Regarding the SIRT genes, we observed that expression of the mitochondria-localizedSIRT3 was significantly downregulated in GL tumors in average, albeit notin all samples, suggesting a potential role of SIRT3 as a discriminant genein the molecular signature of brain tumors." (PMID 25791281, 2015).
cardiac arrest (2 papers, 2019 to 2025). Cessation of breathing and/or cardiac function. "This study aims to examine whether systemic administration of an Annexin-A1 bioactive peptide (ANXA1sp) could resolve neuroinflammation and induce sirtuin-3 regulated cytoprotective pathways in a novel rat model of exsanguinating cardiac arrest and EPR." (PMID 31258464, 2019).
chronic obstructive pulmonary disease (2 papers, 2019 to 2022). A chronic and progressive lung disorder characterized by the loss of elasticity of the bronchial tree and the air sacs, destruction of the air sacs wall, thickening of the bronchial wall, and mucous accumulation in the bronchial tree. "SIRT3 has been shown to be involved in chronic obstructive pulmonary disease (COPD) and PM-induced impairment of airway epithelial cell function." (PMID 36117172, 2022).
Cirrhosis (2 papers, 2012 to 2025). A chronic disorder of the liver in which liver tissue becomes scarred and is partially replaced by regenerative nodules and fibrotic tissue resulting in loss of liver function. "In addition, we observed a trend of decrease in SIRT3 (P = 0.06) and IDH2 (P = 0.05) expression in MASLD and fibrosis, with the most pronounced reduction in patients with cirrhosis." (PMID 41258072, 2025). "There were no statistical connections between SIRT3 expression and the other clinicopathological parameters, such as age, gender, HBsAg, cirrhosis, tumor size and vascular invasion (P>0.05)." (PMID 23272146, 2012).
colorectal tumors (2 papers, 2018 to 2020). "Collectively, these data indicate that SHMT2 K95 acetylation is frequently downregulated in colorectal tumors and is associated with increased SIRT3 expression." (PMID 30367038, 2018). "Together, these results indicate that K88 acetylation of MTHFD2 is downregulated in colorectal tumors and is correlated with highly expressed SIRT3." (PMID 32811824, 2020). "Using an immunohistochemical analysis, we also revealed that levels of SHMT2 were positively correlated with levels of SIRT3 in 309 colorectal tumor samples." (PMID 30367038, 2018). "Thus, K88 acetylation of MTHFD2, MTHFD2 protein and SIRT3 may be potential screening biomarkers for human colorectal tumors." (PMID 32811824, 2020).
delirium (2 papers, 2024 to 2025). A disorder characterized by confusion; inattentiveness; disorientation; illusions; hallucinations; agitation; and in some instances autonomic nervous system overactivity. "There were eight protective genes (DHODH,DHRS7B,TOP1MT,CASP8,GFM1,CPT1B,TK2,GPD2), and four genes (SCP2,DMPK,GSTK1,SIRT3) that increased delirium risk, as shown inFigure 2, withp = 0.05 (dotted line); and false discovery rate (FDR) < 0.05 (red asterisks)." (PMID 41330563, 2025). "Next, we found that overexpression of circRNA_34414 significantly improved the decline in SIRT3 expression and delirium‐like behavior in elderly mice caused by anesthesia/surgery." (PMID 39138637, 2024). "The circRNA_34414 and miR‐6960‐5p overexpression or circRNA_34414 overexpression and SIRT3 downregulation mixed virus counteracted the effect of circRNA_34414 overexpression on postoperative delirium." (PMID 39138637, 2024). "CircRNA_34414 is involved in the improvement of postoperative delirium induced by anesthesia/surgery by upregulating SIRT3 via sponging miR‐6960‐5p." (PMID 39138637, 2024). "Postoperative delirium in elderly mice showed decreased expression of hippocampal circRNA_34414, increased expression of miR‐6960‐5p, decreased expression of SIRT3, and impaired mitochondrial membrane potential." (PMID 39138637, 2024). "In summary, our study found that circRNA_34414 can act as CERNA to block the inhibitory effect of miR‐6960‐5p on SIRT3, thereby participating in the occurrence of postoperative delirium." (PMID 39138637, 2024). "By cell‐type specific overexpression of SIRT3 could significantly protect postoperative delirium." (PMID 39138637, 2024). "After anesthesia/surgery, the reduction in circRNA_34414 levels leads to more miR‐6960‐5p, decreased SIRT3 mRNA, lower SIRT3 protein levels, increased the acetylation of SOD2, which ultimately results in mitochondrial dysfunction and postoperative delirium." (PMID 39138637, 2024).
dementia (2 papers, 2023 to 2025). Loss of intellectual abilities interfering with an individual's social and occupational functions. "The mitochondrial deacetylase known as Sirtuin-3 (SIRT3) is believed to play a crucial part in the mechanisms of OS that are related to dementia." (PMID 40227270, 2025). "In this review, we give an overview of SIRT3’s roles in brain physiology and pathology and discuss several activators of SIRT3 that can be considered potential therapeutic agents for the treatment of dementia." (PMID 36675125, 2023). "Despite all of this, SIRT3 plays an important role as a mediator in maintaining the equilibrium between neuroprotection and oxidative stress, which highlights its potential as a therapeutic target in dementia." (PMID 40227270, 2025).
diabetic retinopathy (2 papers, 2017 to 2024). "Because ROS are also involved in pathogenesis of various eye diseases such as diabetic retinopathy, glaucoma, and age-related macular degeneration, it would be interesting to study the influence of SIRT3 deficiency in these models in the future." (PMID 29214052, 2017).